CAT (catalase)
Diseases named in the same sentence as CAT in open-access papers (continued):
Sharing a sentence is not in itself a finding about the gene and the disease.
tumor (continued). "Nevertheless, in our investigation of the literature, we found that people paid more attention to the +3 state of cerium ions to alleviate inflammation and mimic enzyme activity, while CeOx NP catalase activity was rarely applied to the treatment of tumor hypoxia." (PMID 33343807, 2020). "For late stage malignant cells that had undergone tumor progression, they are protected against exogenous RONS stress by membrane-associated catalase; singlet oxygen mediated catalase deactivation occurs prior to and is critical to H2O2 influx towards cellular redox regulation." (PMID 33202842, 2020). "Furthermore, liposomal NP coated with cisplatin prodrugs and catalase enhanced RT effect and impeded tumor growth, which alleviated cellular hypoxia by triggering the decomposition of H2O2." (PMID 32408880, 2020). "On the other hand, CAT in the nanoparticles could cause the decomposition of endogenous TME H2O2 and generate O2 in situ; thus, it could alleviate the tumor's hypoxia and improve the efficacy of the combination of photodynamic therapy and chemotherapy." (PMID 33343807, 2020). "The activity of catalase increased significantly (p < 0.05) in tumor versus healthy control tissue." (PMID 32899343, 2020). "However, some other tumour treatments take advantage of different gold nanozyme properties, either using their glucose oxidase activity or their catalase activity to alleviate the pernicious effects." (PMID 34138170, 2020). "Their results proved that the combination of CAT and MOFs could play a better role in reducing tumor hypoxia." (PMID 33343807, 2020). "Recently, several studies identified that antioxidant enzyme (catalase) could decompose hydrogen peroxide (H2O2) into H2O and O2, which maybe an effective route for improving tumor reoxygenation and hypoxia-associated radiation resistance." (PMID 32408880, 2020). "The activity of catalase in the tumor, the adjacent, and control healthy tissue was also analyzed." (PMID 32899343, 2020). "Meanwhile, ZSZIT degrades under tumor acidic environment, and H2S produced by ZnS cores could inhibit the expression of catalase, which subsequently favors the hypoxia and antitumor effect of TPZ drug." (PMID 32685012, 2020). "Furthermore, overexpression of catalase was also shown to protect against cancer chemotherapy-induced skeletal muscle dysfunction in a tumor model, as well as suppressing DOX-induced cardiotoxicity in the heart." (PMID 32210013, 2020). "However, in the +4 state, the higher the cerium content is, the more obvious the effect of catalase will be, accompanying the more sustainable and effective the inhibition effect on tumor hypoxia." (PMID 33343807, 2020). "The authors hoped to be able to increase the oxygen content of tumor tissues by catalase." (PMID 32151012, 2020). "CAT is able to catalyse the breakdown of hydrogen peroxide produced by tumor cells." (PMID 32184916, 2020). "This leads to a substantial improvement of combination efficacy by increasing tumour hypoxic conditions, since the CAT-mediated O2 generation could substantially promote an efficient photodynamic therapy operation." (PMID 32272786, 2020). "Moreover, Lactobacillus can exert anticancer effects by producing antioxidants such as glutathione, superoxide dismutase, and catalase, suppressing inflammation and tumor size, and inhibiting the expression of tumor-specific proteins and polyamine components." (PMID 33488940, 2020). "As protection of tumor cells by membrane-associated catalase has been found a regular feature of tumor cells, their reaction was not unexpected." (PMID 31578342, 2019). "The inhibition of CAT activities as a result of tumor growth has also been reported." (PMID 31288458, 2019). "In addition, treatment of PARP1-KO Jurkat cells with APO866 resulted in upregulation of 6 powerful antioxidant genes, including CAT and genes known to increase tumor cell survival such SIRT2 and UCP2." (PMID 31803365, 2019).
tumor (continued). "Furthermore, when the probe reaches the tumor site, catalase can convert high endogenous concentrations of H2O2 to oxygen." (PMID 31534494, 2019). "The development of nanotechnology offers new opportunities to address the shortcomings of conventional designs; inorganic nanomaterials with catalase mimetic properties, such as the MnO2 and carbon nitride-based nanostructures, have been designed to generate oxygen in tumor tissue." (PMID 34138044, 2019). "The reaction of ozone (O3) with certain amino acids from the medium might lead to the generation of 1O293,94 that might target tumor cell protective catalase." (PMID 31578342, 2019). "Due to the parallel expression of NOX1 in the membrane of tumor cells, the attack on catalase by primary 1O2 provokes secondary 1O2 generation, further catalase inactivation, intracellular glutathione depletion and intercellular RONS-mediated apoptosis signaling." (PMID 31578342, 2019). "Using pimonidazole, reduced hypoxia could be detected in tumours from mice injected with HA@mgp-C3N4-HMME/CAT thanks to the formation of O2 through the decomposition of H2O2 compared to mice injected with HA@mgp-C3N4-HMME and irradiated." (PMID 31671658, 2019). "The increase in catalase and superoxide dismutase activity observed in L929dt cells could be an adaptation to oxidative stress by tumor cells that have developed high metastatic potential." (PMID 31330915, 2019). "Another study demonstrated that T cells modified with a bicistronic expression vector chimeric Ag receptor (CAR) co-expressing catalase (CAT) exhibited reduced intracellular oxidative stress which resulted in the increased ability of CAR-CAT T-cells to lyse tumor cells in an antigen-specific manner." (PMID 31426364, 2019). "Marklund and Marklund also reported that tumor growth inhibited catalase and SOD activity." (PMID 30755785, 2019). "Concomitantly, NK cell dysfunction in chronic myelogenous leukemia (CML) is likely to be caused by tumor-produced ROS, since NK cell cytotoxic capacity against primary tumor cells obtained from patients affected with this malignancy was restored in the presence of catalase." (PMID 31535086, 2019). "The protective function of membrane-associated catalase of tumor cells is frequently neglected in the literature, as tumor cells in generally express less catalase than nonmalignant cells." (PMID 31578342, 2019). "The experimental data indicated that GOx and CAT could be released by the stimuli of the mild acidic TME after accumulating at the tumor site." (PMID 31754379, 2019). "generation and catalase inactivation in a population of untreated tumor cells with high efficiency." (PMID 31558835, 2019). "After internalized by tumor cells, the loaded catalase in mCGP was found to catalyze the generated H2O2 to disproportionate into molecular O2 and H2O, accelerating the consumption of endogenous glucose and promoting the production of 1O2 under light irradiation." (PMID 31754379, 2019). "SiRNA-mediated knockdown of catalase or cell-permeable inhibitors of catalase seem to be less promising, as they do not provide selective inhibition of membrane-associated catalase of tumor cells." (PMID 31558835, 2019). "After injection, the oxyhemoglobin saturation level in tumor was increased from about 3% to 17%, demonstrating the nanoparticles with catalase which could decrease hypoxia of tumor, which was helpful for photodynamic therapy." (PMID 30406152, 2018). "Compared with the LGT alone administration group, compatibility with JQC in the ratios (LGT/JQC from 4/1 to 1/4) all significantly reduced LGT-elevated MDA level (P<0.01), and elevated LGT-decreased GSH, GST, GPx, SOD, and CAT levels (all P<0.01) in hepatic of S180 tumor-bearing mice." (PMID 29950302, 2018). "However, since tumour cells lack catalase, they are left vulnerable to the cytotoxic effects of H2O2." (PMID 30217071, 2018).
tumor (continued). "Since catalase is a key enzyme for the resistance against an oxidative stress, ATO could be associated with pro-oxidant drugs to efficiently remove tumor cells." (PMID 29467594, 2018). "Catalase is generally down-regulated in tumor tissues compared with their normal counterparts." (PMID 29467594, 2018). "Therefore, it can be suggested that increasing of CAT activity and involvement of NF-κB are likely mechanisms for the decrease in tumor growth rate observed in VOE250 group." (PMID 29755559, 2018). "In vivo, the proliferative potential and invasiveness of composite tumor xenografts comprising cancerous or non-tumor-forming epithelia with CAFs and FIBs could be attenuated by the presence of catalase." (PMID 28102840, 2017). "This antioxidant status is promoted by an increase in enzymatic antioxidant defense systems mediated by SOD and CAT, which could reflect an attempt to prevent lymph node colonization by tumor cells." (PMID 29264992, 2017). "Increased ROS scavenging, by enhanced expression of antioxidants (SOD, catalase) or decreased pro-oxidant enzyme expression, may decrease oxidative tone and depress tumor growth and migration." (PMID 28578276, 2017). "Interestingly, catalase exhibits higher activity in normal cells where its expression can range on the order of 10- to 100-fold greater than in some tumor cells." (PMID 28107421, 2017). "However, recent studies have shown that Her2 and Ki67 expressions are associated with increased expression of various antioxidant enzymes (superoxide dismutase, catalase, glutathione transferase and glutathione reductase) within the tumor cells." (PMID 29176871, 2017). "Indeed, a reduction in catalase levels in MDA-MB-231 breast cancer cells did result in markedly less tumor formation in the lungs following a tail vein injection." (PMID 27754368, 2016). "Long-term treatment with nelfinavir reduced protein levels of SOD1, SOD2 and catalase in tumor cells, and while it was well established that detoxifying enzymes can be activated and upregulated by ROS, their decrease in oxidative stress condition is not completely understood." (PMID 27280849, 2016). "Relative to normal samples, CAT has been indicated to be downregulated in tumor tissues." (PMID 27034707, 2016). "The inhibition of SOD and CAT activity as a consequence of tumor growth has also been reported." (PMID 25624910, 2015). "Our study was also performed to clarify whether targeting of extracellular catalase of tumor cells by photodynamic therapy might be useful to improve rational and selective tumor therapy." (PMID 26225731, 2015). "Meanwhile, as an H2O2 scavenger, catalase inhibits ROS-mediated tumor metastasis." (PMID 26439801, 2015). "Singlet oxygen-dependent inactivation of tumor cell protective catalase was sufficient to explain the onset of subsequent ROS-mediated apoptosis signaling, as addition of exogenous catalase directly after illumination of MKN-45 tumor cells in the presence of photofrin prevented apoptosis induction." (PMID 26225731, 2015). "Utilization of two characteristic and specific ROS-related features of tumor cell, namely NOX1-dependent generation of extracellular superoxide anions and membrane-associated catalase, warrants strict selectivity of apoptosis induction with respect to the tumor phenotype." (PMID 26225731, 2015). "Thus, we attempted to analyze these correlations further and calculated the tumor/non-tumor tissue (T/N) ratios of HBx, catalase and MnSOD expression levels for each individual sample by tumor stages." (PMID 25361011, 2014). "In addition, high levels of ROS and low levels of catalase have been shown to increase tumor progression, suggesting that catalase functions as a tumor suppressor." (PMID 25361011, 2014). "The catalase (0.1 mg/mL) completely abolished the cytotoxic effects of LmLAAO on MCF-7 tumor cells." (PMID 24940304, 2014).
tumor (continued). "In addition, the solution is directly injected into tumor tissues thereby targeting peroxidase and catalase, which is present in tumor cells." (PMID 24959285, 2014). "Catalase expression was markedly decreased in the exercised plus tumor group." (PMID 24804765, 2014). "Network 3 was characterised by the insertion of a hub protein HNF4alpha, a transcription factor recently shown to play a role in other neoplasias and Network 4 was characterised by numerous mitochondrial-localised proteins (CAT, IDH3A, NDUFS3 and other complex 1 proteins, OXCT1 and PRDX3)." (PMID 24838487, 2014). "The in vivo effects of injecting Conus venom into EAC-tumor-bearing mice, on the activities of representative oxidative defense enzymes (CAT and Cu/Zn-SOD) was examined, together with the effects on cellular GSH (as a non-enzymatic antioxidant) and the total antioxidant capacity (TAC)." (PMID 23849458, 2013). "Protein was extracted from tumor-free, dorsal skin in order to examine catalase activity levels." (PMID 23691100, 2013). "We could show that the tumour cell lines used in the present study are different in their catalase activity." (PMID 22551313, 2012). "In a previous report, we demonstrated that H2O2 scavenging resulted in a significant inhibition of cell proliferation in tumor cells of different origin and we showed herein that catalase treatment or overexpression induced an arrest in the G1 phase of the cell cycle." (PMID 22970236, 2012). "More specifically, alleviation of mitochondrial oxidative stress, via transgenic over-expression of catalase (an anti-oxidant enzyme) targeted to mitochondria, was sufficient to lower tumor grade (from high-to-low) and to dramatically reduce metastatic tumor burden by >12-fold." (PMID 21605374, 2011). "In conclusion, the results of our study indicate that the GOX/CAT system might be a useful tool for the in vitro investigation of tumor hypoxia." (PMID 21477371, 2011). "Both SOD and CAT activities were reported to be lower as a result of tumor growth." (PMID 22319252, 2011). "In fact, a lower capacity to destroy H2O2 e.g., by catalase, peroxiredoxins, and GSH peroxidases may cause tumor cells to grow and proliferate more rapidly than normal cells in response to low concentrations of H2O2." (PMID 21080962, 2010). "The results showed that catalase inhibited the enhanced tumour cell adhesion after X–XO preincubation effectively as well, that is, for HT29 adhesion decreased from 167 to 141% (P<0.05), for Caco2 from 158 to 113% (P<0.01), and for PanC1 from 299 to 163% (P<0.01)." (PMID 17088916, 2006). "This in turn might actually cause an oxidative environment in the organ along with increased CAT and GPx activities with detrimental effects to tumor cells." (PMID 17107616, 2006). "TPA is a potent tumour promoter and treatment with this compound of the two cell lines induced peroxisomal fatty acid beta-oxidation, carnitine acetyltransferase, palmitoyl-CoA hydrolase, and catalase activities after 240 h of treatment." (PMID 2868750, 1986). "Second, variability in CAT expression may reflect tumor heterogeneity and disease progression." (PMID 41009025, 2025). "To confirm that the increased tumor rejection was due to mROS damage to the mtDNANZB Treg cells, we generated a mouse strain that expresses cre-recombinase conditional mitochondrial targeted catalytic antioxidant catalase (mCAT) from within the Rosa26 locus (Rosa26-LSL-mCAT or mCATfl)." (PMID 39752523, 2025). "Doxorubicin has also been shown to reduce cardiac catalase activity with 9-week treadmill running exercise performed concomitantly with doxorubicin treatment, increasing catalase activity and the activity of other antioxidative enzymes in tumor-free female rats." (PMID 38725573, 2024). "Additionally, using this nanoplatform to deliver catalase (CAT) to the local tumor effectively avoids proteinase-induced degradation, instability, and immunogenicity that could arise from exogenous protein entry into the body." (PMID 38139233, 2023).
tumor (continued). "Hence, reduction of hydrogen peroxide by catalase could slow tumor growth by disrupting these pro-tumorigenic signaling pathways." (PMID 37311396, 2023). "Therefore, tumor cells must require strong ROS-scavenging systems (such as HO-1, superoxide dismutase, catalase, peroxiredoxin, thioredoxin, glutaredoxin, and glutathione peroxidase) to eliminate ROS, in which the HO-1 antioxidant system plays an important role." (PMID 37765244, 2023). "In conclusion, we observe that sustained intratumoral catalase neither has therapeutic benefit nor triggers significant differential expression of genes associated with the anticipated therapeutic mechanism in the subcutaneous syngeneic tumor models used." (PMID 37311396, 2023). "Similarly, other studies have reported decreased levels of GSH and CAT in tumor tissue." (PMID 36232966, 2022). "Notably, the PpIX FL intensity obtained by MN-CCPCA treatment (12 h) was 2.2-fold higher than that obtained by MN-CCPA (12 h) treatment at the METP of PpIX, indicating that 5-ALA and CAT co-delivery could promote PpIX tumor accumulation in vivo." (PMID 36266306, 2022). "However, CAT expression is highly expressed in other cancer cells, which require high antioxidant detoxifying systems and upregulation of CAT for tumor progression and metastasis to compensate for high ROS production and to prevent ROS-mediated cell death processes." (PMID 36112236, 2022). "The catalase- and peroxidase-like performance of these MXene-based nanozymes alleviated hypoxia and elevated oxidative stress in the tumor microenvironment; they also exhibited excellent capability for the degradation of glutathione to improve the tumor ablation." (PMID 36333561, 2022). "Furthermore, by transferring H2O2 to O2, the GOx/CAT-NCs could be applied to spatiotemporally controlled cancer therapy by reducing tumor hypoxia." (PMID 34577080, 2021). "An increased expression of aquaporins by tumor cells thus may reflect the necessary response of the cells to cope with limited supply with exogenous H2O2, which is caused by H2O2 decomposition by membrane-associated catalase." (PMID 34679719, 2021). "The over-expression of folate (FA) receptor on tumor cells including breast, lungs, kidneys, ovaries, colon, brain, etc. has also been exploited for delivery of FA-modified oxygen-based NCs to tumors, such as FA-modified CAT-based liposomes for breast tumor hypoxia alleviation." (PMID 34277702, 2021). "One study showed that equol suppressed tumor formation in rats, presumably through decreasing the concentrations of thiobarbituric acid-reactive substances and 8-hydroxy-2-deoxyguanosine, and increasing the activity of catalase, SOD, and glutathione peroxidase." (PMID 34835997, 2021). "Additionally, in the in vivo results, compound 4 inhibited the tumor proliferation by 48.4% compared to 29.28% for 5-FU, activated antioxidants (CAT, SOD and GSH) levels, and ameliorated hematological and biochemical parameters, as well as histopathological examinations." (PMID 35011314, 2021). "In addition to natural catalase, nanozymes, synthetic nanomaterials with inherent enzyme-like characteristics, can also be designed with a range of enzymatic activity and have been explored as potential solutions to ameliorate tumor hypoxia during PDT." (PMID 34138222, 2021). "In addition, enzymatically active catalase in the RBC membrane could metabolize tumor endogenous H2O2 and ameliorate tumor hypoxia." (PMID 32046010, 2020). "Furthermore, the catalase-mimicking DNA enzyme function of G-quadruplexes and hemin could react with tumor endogenous H2O2 to generate oxygen for enhanced PDT by overcoming the hypoxia-associated resistance." (PMID 32641993, 2020). "Similarly, CTLs armed with engineered T cell receptors (CAR-T cells, chimeric antigen receptor-redirected T cells) that co-expressed catalase were secured from oxidative stress and preserved high tumor killing activity indicating that hydrogen peroxide participates to T cell anergy." (PMID 32630174, 2020).